EGF (epidermal growth factor)
Diseases named in the same sentence as EGF in open-access papers (continued):
Sharing a sentence is not in itself a finding about the gene and the disease.
melanoma (continued). "Moreover, in stage IV melanoma patients with brain metastases, CCL18, CCR1, CCR4, CD274, CSF2, EGF, and PTGS2 genes were significantly over-expressed (p < 0.001, versus patients without melanoma brain metastasis)." (PMID 37091783, 2023). "Patient-derived BRAFV600E melanoma cells could grow without serum and exogenous growth factors, FGF2, EGF (epidermal growth factor), and HGF (hepatocyte growth factor), for at least 4 months without substantial changes in viability and cell phenotype." (PMID 31167513, 2019). "Neither the cell cycle nor the activity of pathways important for melanoma maintenance, such as MAPK-ERK, WNT (wingless/integrated)/β-catenin, and NF-κB (nuclear factor kappa B), were affected by the absence or presence of FGF2, HGF, and EGF used alone or in combination." (PMID 31167513, 2019).
hepatocellular carcinoma (95 papers, 2004 to 2025). A malignant tumor that arises from hepatocytes. "The association between epidermal growth factor (EGF) gene +61A/G polymorphism (rs4444903) and hepatocellular carcinoma (HCC) susceptibility has been widely reported, but the results were inconsistent." (PMID 25927412, 2015). "We also identified a signaling pathway implicated in EGF-induced hepatoma cell migration in which GEP100 was present." (PMID 22701712, 2012). "Odds ratios and 95% confidence intervals reported for the association between hepatocellular carcinoma and EGF 61*A/G genotype." (PMID 22403631, 2012). "Epidermal growth factor (EGF) signaling is implicated in the invasion and metastasis of hepatoma cells." (PMID 22701712, 2012). "Previous work suggests an association between the EGF 61*A/G polymorphism (rs4444903) and susceptibility to hepatocellular carcinoma (HCC), but the results have been inconsistent." (PMID 22403631, 2012). "According to the disease module of the BIOBASE Knowledge Library (BKL), EGF-induced carcinogenesis caused differential expression of 39 known biomarker genes associated with liver carcinoma/neoplasms." (PMID 21464922, 2011). "It is, perhaps, not surprising that proliferation and inflammation pathways are linked responses to EGF in endometrial carcinoma-derived cells, as has been observed in other models of cancer including hepatocellular carcinoma." (PMID 20579378, 2010). "We have previously reported increased stability of EGF 61*G allele transcripts compared to EGF 61*A allele transcripts in human hepatoma cell lines and primary human hepatocytes as well as increased levels of serum and liver EGF in subjects with cirrhosis who have the EGF GG versus AA genotype." (PMID 25504078, 2014). "Here, we wished to analyze gene expression profiles of pre-tumorous and highly differentiated hepatocellular carcinomas with a novel computational method that enabled identification of regulators of the EGF signalling cascade associated with malignant transformation." (PMID 21464922, 2011). "In hepatocellular carcinoma, an oncogenic EGF-EGFR-PI3K/Akt pathway was shown to increase p300 HAT-mediated H3K9 acetylation of the HMGA2 promoter, resulting in higher HMGA2 gene expression and a poor prognosis." (PMID 36835656, 2023). "In hepatocellular carcinoma cells, EGF and IFN-γ both activated PD-L1 expression via the MAPK signaling pathway, which can be blocked by the MEK inhibitor selumetinib." (PMID 37759950, 2023). "Primary rat hepatocytes and human hepatoma HepaRG cells also require mitogenic stimulation by epidermal growth factor (EGF) to undergo cell division for proper assessment of the potential to induce MN." (PMID 37046355, 2023). "The recombinant human a1-acid glycoprotein or recombinant human epidermal growth factor functionalized nanoparticles were taken up by macrophages and hepatocellular carcinoma cells." (PMID 35010124, 2022). "Epidermal growth factor (EGF) partly mimics the serum effects in hepatoma cells, and EGF effect can be blocked by ERK inhibitors." (PMID 33142929, 2020). "In the present study, we demonstrate that DHW inhibits the proliferation of hepatoma cells by modulating the EGF signaling pathway." (PMID 32298294, 2020). "In this study, we found that DHW inhibits the proliferation of hepatoma cells by modulating the epithelial growth factor (EGF) signaling pathway." (PMID 32298294, 2020). "In this study, we first demonstrated that DHW inhibits the proliferation of hepatoma cells by modulating EGF signaling." (PMID 32298294, 2020). "We have observed rapamycin inhibited the EGF-induced down-regulation of PDCD4 mRNA levels in Huh7 hepatoma cells." (PMID 31075975, 2019). "The association of epidermal growth factor (EGF) gene +61A/G polymorphism (rs4444903) and hepatocellular carcinoma (HCC) has been investigated in several populations." (PMID 29379593, 2017).
hepatocellular carcinoma (continued). "Our previous studies showed that GALNT2 modulated EGFR activity and suppressed EGF-induced proliferation, migration, and invasion in hepatocellular carcinoma cells." (PMID 26848976, 2016). "Meanwhile, our data supported the concept that EGF is capable of inducing ERK and Rac1 activation through the Arf6 pathway, and this process is associated with hepatoma cell migration where GEP100 was present." (PMID 22701712, 2012). "Our results demonstrate that EGF stimulates hepatoma HepG2 cell migration through GEP100-dependent activation of the Arf6/ERK/Rac1 signaling pathway." (PMID 22701712, 2012). "Recent studies indicated that EGFR is frequently expressed in human hepatoma cells, and EGF is one of the mitogens that is needed for the growth of hepatoma cells." (PMID 22860012, 2012). "Taken together, this study highlights the function of the PH domain of GEP100 and its regulated Arf6/ERK/Rac1 signaling cascade in EGF-induced hepatoma cell migration." (PMID 22701712, 2012). "We found that EGF dose-dependently stimulated the migration of human hepatoma cells HepG2, with the maximal effect at 10 ng/mL." (PMID 22701712, 2012). "Serum EGF levels were 1.8-fold higher in G/G hepatocellular carcinoma patients with cirrhosis than A/A patients, and liver EGF levels were 2.4-fold higher in G/G patients than A/A patients." (PMID 20487573, 2010). "Additionally, anthocyanins have been shown to inhibit the epithelial-mesenchymal transition of hepatocellular carcinoma cells triggered by epidermal growth factor." (PMID 39940837, 2025). "Similarly, irradiation of hepatoma cells has been linked to the secretion of tumor necrosis factor-alpha (TNF-α), IL-6, VEGF, epidermal growth factor (EGF), MMP2, and MMP9, all of which enhance tumor invasion." (PMID 39759518, 2024). "HuR targets include invasive and metastatic RNAs (e.g., MMP-9, MTA1, and uPA), angiogenic RNAs (e.g., VEGF-1 and HIF-1), and cell proliferative RNAs (e.g., EGF, cyclin A, cyclin B1, cyclin E, and cyclin D1), through which it can influence hepatocellular carcinoma progression." (PMID 37540723, 2023). "We herein summarize and discuss studies focused on partial hepatectomy and liver carcinogenesis, referring to hepatocyte growth factor, insulin-like growth factor, and epidermal growth factor, as well as their suitability as targets in the treatment of hepatocellular carcinoma." (PMID 34572344, 2021). "When proliferation of the human hepatoma cell line SMMC-7721 was measured in the presence of 1 μg/mL of GE11 or EGF over 48 h, treatment with GE11 resulted in an increase in proliferation of approximately 10% while treatment with EGF stimulated a 50% increase in growth." (PMID 34831131, 2021). "However, LCN2 negatively modulates epithelial–mesenchymal transition (EMT) in hepatocellular carcinoma cells through the epidermal growth factor (EGF) or transforming growth factor (TGF)-β1/LCN2/Twist1 pathway." (PMID 34202288, 2021). "Here, our results also suggested that nuclear PKM2 could serve as a transcriptional cofactor to induce PD-L1 transcription in response to EGF stimulation in hepatocellular carcinoma cells." (PMID 33324209, 2020). "In this study, we found that DHW inhibits hepatoma cell proliferation by blocking EGF signaling." (PMID 32298294, 2020). "In addition, EGF-TCS also has in vivo anti-hepatoma effects when the hepatoma animal model is constructed by injection of BEL-7402 cells." (PMID 23377374, 2013). "Therefore, EGF directly activates the migration of hepatoma cells, which is a critical step for tumor metastasis." (PMID 22701712, 2012). "These experiments suggest that ENMD-1198 may effectively interfere with crucial EGF-mediated and angiogenesis-related signaling cascades in hepatocellular carcinoma cells." (PMID 18651980, 2008).
hepatocellular carcinoma (continued). "to investigate the correlation between the epidermal growth factor (EGF) polymorphism and the risk of hepatocellular carcinoma (HCC) in hepatitis C viral (HCV) cirrhotic patients as well as its relation to EGF protein expression in HCC tissue." (PMID 32711431, 2020). "The tyrosine kinase inhibitor erlotinib targets the receptor of epidermal growth factor (EGFR) involved in development of hepatocellular carcinoma (HCC)." (PMID 28915658, 2017). "Transgenic mice with liver-targeted overexpression of the secreted EGF fusion protein develop hepatocellular carcinoma, and blockade of EGF receptor activity halt the development and progression of HCC." (PMID 25927412, 2015). "Indeed, EGF is overexpressed in the fibrotic liver, plays a central role during liver regeneration, and is member of a 186-gene signature predictive of progressive cirrhosis, hepatocellular carcinoma, and death in patients with cirrhosis." (PMID 26251672, 2015). "The present study aimed at investigating the role of EGF-EGFR signalling pathway in the development of human hepatocellular carcinoma (HCC) inflammatory environment." (PMID 24268047, 2014). "However, the signaling pathways for EGF-induced motility of hepatoma cells remain undefined." (PMID 22701712, 2012). "We wished to examine whether Arf6 influenced cell migration in hepatoma cells after EGF treatment." (PMID 22701712, 2012). "The GALNT5 gene, part of the GALNT family, enhances EGF/EGFR activation in cancers like cholangiocarcinoma, hepatocellular carcinoma, and ovarian cancer." (PMID 40739397, 2025). "MUC15 was with decreased expression in hepatocellular carcinoma (HCC), and its overexpression significantly suppressed EGF induced dimerization of EGFR and activation of PI3K-AKT pathway, which finally inhibited tumor cell migration and invasion." (PMID 40225867, 2025). "This regulatory mechanism is corroborated in hepatocellular carcinoma (HCC) cells, where EGF-induced ERK1/2 activity drives TNS4 upregulation." (PMID 40906372, 2025). "A study in hepatocellular carcinoma reported that gefitinib significantly inhibits the upregulation of VEGF and CXCL1 induced by EGF stimulation, thereby suppressing angiogenesis." (PMID 38918360, 2024). "Moreover, HDGFRP3 increases the basal level of ERK phosphorylation/activation and enhances the duration of EGF-mediated activation of ERK1/2 in hepatocellular carcinomas cells, suggesting that HDGFRP3 may serve as a novel molecular target for treatment of hepatocellular carcinomas." (PMID 36794849, 2023). "TsIIA inhibited the proliferation of hepatoma cell line SMMC-7721 and induced apoptosis in a concentration dependent manner, and down regulated the expression of EGF and EGFR." (PMID 36798821, 2023). "As EGFR activation is required for productive HCV entry and ADAMs can shed EGF, we asked if ADAM10 also transactivates EGFR in human hepatoma cells." (PMID 37967063, 2023). "The CAFs produce angiogenic factors, such as VEGF, TGF-β1, EGF, Ang-1, Ang-2, PDGF, MMPs, and FDF, which are essential for hepatocellular carcinoma (HCC) initiation, progression, and metastatic development, as well as the growth of new vessels." (PMID 36419156, 2022). "In the 1990s, researchers reported the use of ITs of TCS with Hepama-1 (human hepatoma), CMU15A (Lung cancer antigen), anti-p75-anti-mouse IgG (p75: nerve growth factor), Ng76 (Melanoma), and EGF (hepatocellular carcinoma)." (PMID 35324675, 2022). "New chimeric inhibitors targeting the epidermal growth factor (EGFR) and histone deacetylases (HDACs) were synthesized and tested for antineoplastic efficiency in solid cancer (prostate and hepatocellular carcinoma) and leukemia/lymphoma cell models." (PMID 34445133, 2021). "Repressing Brf1 expression inhibits the EGF-stimulated cell transformation, whereas DEN (diethylnitrosamine), a potent chemical hepatocarcinogen, has widely been used to induce HCC (hepatocellular carcinoma) in rodents." (PMID 31781337, 2019).
hepatocellular carcinoma (continued). "In HER2‐overexpressed hepatoma cells, HepG2, JM1, and HER2‐transfected McA cells, phosphorylated levels of HER2, AKT, ERK, and β‐catenin were increased at 10 minutes after EGF stimulation." (PMID 30714677, 2019). "EGF plays a role in liver fibrosis, liver cirrhosis, and even hepatocellular carcinoma (HCC)." (PMID 28691020, 2017). "FGF- β, EGF and TGF- β treatment enhances the α1β1- and α2β1-mediated migration of hepatocellular carcinoma cell lines." (PMID 25874996, 2015). "RAB5A, overexpressed in hepatocellular carcinomas, seems to be determinant for liver cancer progression, as suggested by the finding that a dominant negative form of RAB5A attenuates EGF-mediated signalling and cell migration of a human hepatoma cell line." (PMID 22724020, 2012). "In the setting of chronic liver injury in humans, epidermal growth factor (EGF) and EGF receptor (EGFR) are up-regulated and have been proposed to have vital roles in both liver regeneration and development of hepatocellular carcinoma (HCC)." (PMID 20618941, 2010). "Additionally, epidermal growth factor (EGF)-induced extracellular regulated protein kinase 1/2 (ERK1/2) upregulates TNS4, promoting proliferation and migration in hepatocellular carcinoma." (PMID 40906372, 2025). "In the human hepatocellular carcinoma cell line HepG2, daphnetin did not inhibit EGF-induced tyrosine phosphorylation of the EGF receptor." (PMID 37371063, 2023). "In hepatocellular carcinoma cell lines, PKM2 could be phosphorylated at Ser37 by EGF receptor-activated extracellular signal-regulated kinase when stimulated with EGF, which promoted its nuclear translocation." (PMID 37196116, 2023). "In one study, dendrimers conjugated with epidermal growth factor (EGF), human serum albumin (HSA) and nimotuzumab antibody (h-R3) were used to deliver siRNA against polo-like kinase-1 (PLK1) to the EGFR-overexpressing hepatocellular carcinoma cell line (HepG2) and tumor-bearing BALB/c nude mice." (PMID 33805602, 2021). "Since EGF signaling is critical for the proliferation of hepatoma cells, we then further explored whether DHW inhibits hepatoma cell proliferation by regulating EGF signaling." (PMID 32298294, 2020). "Analysis of wild-type Shp2 and SUMOylation-defective Shp2K590R mutant reveals that SUMOylation of Shp2 promotes EGF-stimulated ERK signaling pathway and increases anchorage-independent cell growth and xenografted tumor growth of hepatocellular carcinoma (HCC) cell lines." (PMID 25823821, 2015). "In cultured rat hepatocytes, inin vitro experiments, serotonin induces dose-dependent increase in DNA synthesisonly in the presence of insulin and epidermal growth factor (EGF) and recently serotonin has been shown to promotehepatocellular cancer growth in human hepatocellular cancer cell lines." (PMID 25433672, 2014). "However, when epidermal growth factor (EGF) is conjugated to TCS, the immunotoxin EGF-TCS is toxic to hepatoma cells, for example, BEL-7402, MCF-7, and BGC-823." (PMID 23377374, 2013). "In addition to initial findings in cultured hepatocellular carcinoma, we now show that Enz inhibits the in vitro migration and invasion of NSCLC cells, and that EGF-induced invasion is countered by Enz, which is a major pathway in NSCLC progression." (PMID 20736951, 2010). "Daphnetin could inhibit EGF-induced tyrosine phosphorylation of EGF receptor in the presence of ATP in vitro, whereas it could not repress EGF-induced tyrosine phosphorylation of EGF receptor in human hepatocellular carcinoma HepG2 cells." (PMID 34956168, 2021). "Previous studies reported that silencing of GALNT2 could inhibit insulin-induced insulin receptor activation and Akt phosphorylation in hepatoma cells, whereas overexpression of GALNT2 in oral cancer cells could promote EGF-induced phosphorylation of EGFR and Akt." (PMID 32559179, 2020).
hepatocellular carcinoma (continued). "Both EGF- and HBEGF- induced AREG may increase cell proliferation, anchorage-independent growth, and reduce apoptosis in an almost autocrine manner, as shown for hepatocellular carcinoma." (PMID 27669890, 2016). "Furthermore, cell culture experiments showed that even isolated egg proteins alone are sufficient to induce expression of MCM7 in human hepatoma cells without the involvement of the generally accepted paracrine-triggered mechanism by mitogens such as interleukin 6 and EGF." (PMID 37696392, 2024). "A study showed that miR-486-3p can adjust the sorafenib response in hepatocellular carcinoma (HCC), targeting both fibroblast growth factor receptor 4 (FGFR4) and epidermal growth factor (EGFR), and adjusts it to be a better treatment target than FGFR4 and EGFR inhibitors." (PMID 35215154, 2022). "Indeed, we show here that EGF-induced Arf6 activation could be suppressed by ectopic expression with GEP100 siRNA as well as GEP100-△PH, so we suggest that the PH domain of GEP100 is involved in EGF signaling to induce Arf6 activation and migration of human hepatoma HepG2 cells." (PMID 22701712, 2012).